CENPVL2 (centromere protein V like 2)
Synonyms: CENPVP2
Tractability: No criterion of Open Targets' tractability assessment is met for any kind of drug.
Gene: Protein-coding gene on chromosome X (51,681,212 to 51,682,831, reverse strand). Ensembl gene ENSG00000283093.
Gene Ontology:
Molecular function: carbon-sulfur lyase activity
Homologues: Orthologues: chimpanzee CENPVL3 (96% identical), macaque CENPVL3 (94% identical), tropical clawed frog cenpv (39% identical), zebrafish cenpv (29% identical), Caenorhabditis elegans F25B4.8 (19% identical). Paralogues in human: CENPVL1 (100% identical), CENPVL3 (96% identical), CENPV (51% identical).
Diseases named in the same sentence as CENPVL2 in open-access papers:
CENPVL2 is named in the same sentence as 3 diseases in open-access papers, as found by Europe PMC text mining. Sharing a sentence is not in itself a finding about the gene and the disease.
CENPVL2 shares sentences with these, for which no sentence is quoted: developmental delay (1 paper); Intellectual disability (1); X-linked intellectual disability (1).